MLKL (mixed lineage kinase domain like pseudokinase)
Diseases named in the same sentence as MLKL in open-access papers (continued):
Sharing a sentence is not in itself a finding about the gene and the disease.
chronic lung disease (1 paper, 2020). According to the definitions of the American and British Thoracic Societies, including pulmonary functional tests, X-rays, and CT scans for items such as fibrosis, bronchiectasis, bullae, emphysema, nodular or lymphomatous abnormalities. "Programmed necrosis (necroptosis) is a cellular program regulated by RIPK1 (receptor-interacting protein kinase 1) and RIPK3, and MLKL (mixed lineage kinase domain-like pseudokinase) in chronic lung diseases." (PMID 32357474, 2020).
chronic myelomonocytic leukemia (1 paper, 2024). A myelodysplastic/myeloproliferative neoplasm which is characterized by persistent monocytosis, absence of a Philadelphia chromosome and BCR/ABL fusion gene, fewer than 20 percent blasts in the bone marrow and blood, myelodysplasia, and absence of PDGFRA or PDGFRB rearrangement. "RNA-Seq investigation of CD34+ bone marrow cells from MDS or chronic myelomonocytic leukemia (CMML) patients revealed an overexpression of the necroptotic executor MLKL and its relationship with anemia severity." (PMID 38730609, 2024).
Constipation (1 paper, 2025). Infrequent or difficult evacuation of feces. "The downregulation of CASP3, GSDMD, and MLKL expression observed after HP treatment suggests that its protective effects on epithelial barrier integrity and anti-inflammatory properties may have broader therapeutic applications beyond constipation." (PMID 41050658, 2025). "This study shows that MLKL and its upstream regulatory molecule ZBP1 expression increases in the constipation model, suggesting a potential backup death mechanism triggered by microenvironmental stress, such as inflammation or cytokine stimulation." (PMID 41050658, 2025).
cutaneous vasculitis (1 paper, 2019). Inflammation of the blood vessel wall characterized by palpable purpura. "As we already mentioned, phosphorylation of MLKL in the infiltrated human neutrophils was also found in cutaneous vasculitis and psoriasis." (PMID 31719524, 2019).
diabetic cardiomyopathy (1 paper, 2022). Diabetic cardiomyopathy is a disorder of the heart muscle in people with diabetes. "Lastly, shRNA-mediated knockdown of MLKL provided an in vivo potential gene therapy to reduce diabetic cardiomyopathy by targeting necroptosis signaling." (PMID 36030201, 2022). "To determine the role of RIPK3 in MLKL phosphorylation and diabetic cardiomyopathy, we induced type-1 diabetes in RIPK3 knockout and wild-type mice by STZ injection." (PMID 36030201, 2022). "In summary, we have provided evidence that cardiomyocyte necroptosis plays an important role in mediating cardiac pathology of type-1 diabetes and that MLKL-mediated necroptosis contributes to diabetic cardiomyopathy." (PMID 36030201, 2022). "In this study, we characterized cardiomyocyte necroptosis in diabetic hearts and examined the role of MLKL-mediated necroptosis in diabetic cardiomyopathy." (PMID 36030201, 2022). "We have provided evidence that cardiomyocyte necroptosis is present in diabetic hearts and that MLKL-mediated cardiomyocyte necroptosis contributes to diabetic cardiomyopathy." (PMID 36030201, 2022).
diabetic nephropathy (1 paper, 2022). "In this study, we confirmed that renal tubular cells undergo necroptosis in diabetic nephropathy and obtained the same results in experiments in vitro by measuring RIP1, RIP3, and MLKL levels, which are the sensitive biomarkers of the necroptosis signaling pathway." (PMID 35280997, 2022).
diabetic neuropathy (1 paper, 2025). A chronic, pathological complication associated with diabetes mellitus, where nerve damages are incurred due to diabetic microvascular injury involving small blood vessels that supply these nerves, resulting in peripheral and/or autonomic nerve dysfunction. "Moreover, the activation of MLKL and the MLKL-induced myelin breakdown were observed in patients with diabetic neuropathy." (PMID 40002826, 2025).
diffuse large B-cell lymphoma (1 paper, 2023). "The StemnessScores in both RNAss and DNAss were negatively correlated with FASLG and MLKL expressions in cancers such as Lymphoid Neoplasm Diffuse Large B-cell Lymphoma (DLBC), GBM, KICH, and LUSC." (PMID 37000317, 2023).
Enterococcus faecalis infection (1 paper, 2021). A bacterial infection induced by Enterococcus faecalis which is the most prevalent species (along with Enterococcus faecium) cultured from humans, accounting for more than 90% of clinical isolates. "Inhibitors of RIPK3 and MLKL suppressed cell death from Enterococcus faecalis infection in MG-63 cells." (PMID 34400895, 2021).
esophageal squamous cell carcinoma (1 paper, 2021). Esophageal squamous cell carcinoma (ESCC) is a type of esophageal carcinoma (EC) that can affect any part of the esophagus, but is usually located in the upper or middle third. "We also investigated the correlations between the status of MLKL/pMLKL and tumor-infiltrating lymphocytes) in esophageal squamous cell carcinoma patients." (PMID 34503283, 2021).
fungal infection (1 paper, 2020). "Combined with the reduced activation of caspase-3, -7 and MLKL, these findings suggest cells undergo reduced cell death when crucial components of PANoptosis are missing during fungal infection." (PMID 33109609, 2020).
Granuloma (1 paper, 2017). A compact, organized collection of mature mononuclear phagocytes, which may be but is not necessarily accompanied by accessory features such as necrosis. "Immunocytochemical staining for MLKL phosphorylation further demonstrated the occurrence of necroptosis in vivo in murine M. tuberculosis granulomas." (PMID 28892415, 2017).
hematoma (1 paper, 2025). A hematoma is a collection of blood from a vascular structure into an extravascular space. "Even if adjusting for NIHSS scores and hematoma volume, serum MLKL levels were still linearly correlated with the risk of poor prognosis (p for nonlinear > 0.05)." (PMID 40079614, 2025). "Noteworthily, Serum MLKL levels, alongside NIHSS scores and hematoma volume, were independently associated with END and poor prognosis six months after ICH." (PMID 40079614, 2025). "Specifically, even if adjusting for NIHSS scores and hematoma volume, serum MLKL levels were still linearly correlated with END and poor prognosis six months after ICH." (PMID 40079614, 2025). "The addition of all five parameters in a multiple factorial model led to the finding that hematoma volume (OR, 1.064; 95% CI, 1.012–1.120; p = 0.012) and serum MLKL levels (OR, 1.902; 95% CI, 1.229–2.945; p = 0.014) were independent associated with END." (PMID 40079614, 2025). "Furthermore, the models of END and poor prognosis were built, in which NIHSS scores, hematoma volume, and serum MLKL were merged." (PMID 40079614, 2025). "After adjusting for NIHSS scores and hematoma volume, the linear relationship still existed between serum MLKL levels and END risk (p for nonlinear > 0.05)." (PMID 40079614, 2025). "Serum MLKL levels were tightly correlated with NIHSS scores (p < 0.001), hematoma volume (p < 0.001), blood glucose levels (p < 0.01), and intraventricular hemorrhage (p < 0.01)." (PMID 40079614, 2025). "The models integrating serum MLKL levels, NIHSS scores, and hematoma volume were graphically represented by nomogram and predicted END and poor prognosis with a good consistency under the calibration curve." (PMID 40079614, 2025). "The predictive ability of serum MLKL levels resembled those of NIHSS scores and hematoma volumes (both p > 0.05)." (PMID 40079614, 2025). "Moreover, serum MLKL, NIHSS scores, and hematoma volume were put together to construct an END prediction model of representation by a nomogram, and the model presented with a good steadiness." (PMID 40079614, 2025). "Moreover, post‐ICH serum MLKL levels showed an independent correlation with NIHSS scores, hematoma volume, and poststroke six‐month mRS scores." (PMID 40079614, 2025). "Moreover, the prediction model with the consolidation of serum MLKL levels, NIHSS scores, and hematoma volume was visualized via a nomogram and had good stability." (PMID 40079614, 2025). "In our study, serum MLKL levels had similar AUC to NIHSS scores and hematoma volume, signifying that serum MLKL may be clinically valuable in anticipation of END and poor prognosis in ICH, hopefully leading to improvement of patient outcomes or refinement of risk stratification methods." (PMID 40079614, 2025). "In addition, as for predicting END and poor prognosis following acute ICH, serum MLKL levels at admission presented with analogous AUC as those at other time‐points among those seventy‐three patients, and the results were consistent when compared to NIHSS scores and hematoma volume in all patients." (PMID 40079614, 2025).
hemorrhagic stroke (1 paper, 2024). A stroke caused by a bleed on the brain. "Mixed Lineage Kinase Domain-Like Protein (MLKL), as the executor of necroptosis and a critical factor in the inflammation, has been shown to be associated with the progression of hemorrhagic stroke." (PMID 39902279, 2024). "Proteomic analysis indicates that co-targeting MLKL and its associated protein network may yield better therapeutic outcomes for hemorrhagic stroke." (PMID 39902279, 2024).
Hepatic cysts (1 paper, 2021). "The AIH-n group had significantly higher mRNA expression of RIP3 and MLKL than the hepatic cyst group." (PMID 33841405, 2021).
Hydrocephalus (1 paper, 2021). Hydrocephalus is an active distension of the ventricular system of the brain resulting from inadequate passage of CSF from its point of production within the cerebral ventricles to its point of absorption into the systemic circulation. "We further showed that the RIP1 kinase inhibitor Nec‐1 and the RIP3 kinase inhibitor GSK872 exert neuroprotective effects against necroptosis by inhibiting the RIP1/RIP3/MLKL pathway and inflammation after hydrocephalus." (PMID 34374150, 2021). "We found that p‐RIP3 and p‐MLKL were mainly colocalized with NeuN+neurons in the hippocampus and cortex after hydrocephalus induction." (PMID 34374150, 2021). "We further found that p‐RIP3 and p‐MLKL expression in the cortex and hippocampus increased after hydrocephalus." (PMID 34374150, 2021). "In the present study, we demonstrated that RIP1/RIP3/MLKL‐mediated necroptosis contributes to necrotic cell death after kaolin‐induced hydrocephalus in mice." (PMID 34374150, 2021). "RIP1/RIP3/MLKL mediates necroptosis in the cortex and hippocampus in a hydrocephalus mouse model, and Nec‐1 and GSK872 have some neuroprotective effects." (PMID 34374150, 2021). "In a hydrocephalus mouse model, Nec‐1 and GSK872 reduce necrotic cell death, effectively inhibit the phosphorylation of RIP3 and MLKL, and reduce the levels of inflammatory factors such as IL‐1β, IL‐6 and TNF‐α in the cortex and hippocampus." (PMID 34374150, 2021). "Obvious pathological changes appeared in the hippocampus and cortex after hydrocephalus, and expression of the necroptosis markers p‐RIP3, p‐MLKL and inflammatory cytokines increased." (PMID 34374150, 2021). "Moreover, p‐RIP3 and p‐MLKL were mainly colocalized with neurons but not astrocytes or microglia in the hippocampal cortex after hydrocephalus." (PMID 34374150, 2021).
hyperthyroidism (1 paper, 2023). Overactivity of the thyroid gland resulting in overproduction of thyroid hormone and increased metabolic rate. "Our findings reveal that GD hyperthyroidism aggravates cognitive deficits in AD mice and induces Aβ deposition and neuronal loss by inducing neuroinflammation and RIPK3/MLKL-mediated necroptosis." (PMID 37740205, 2023). "In conclusion, our findings suggest that GD hyperthyroidism aggravates cognitive deficits and Aβ deposition in mice by inducing neuroinfammation and RIPK3/MLKL-mediated necroptosis in the brain." (PMID 37740205, 2023).
intervertebral disc degeneration (1 paper, 2022). "Furthermore, inhibition of MLKL by NSA was able to reverse the interleukin‐1β‐induced nucleus pulposus cell death, suggesting that NSA could protect intervertebral disc degeneration via necroptosis and apoptosis inhibition." (PMID 35106914, 2022).
intestinal tumors (1 paper, 2021). "Herein, we demonstrated that loss of MLKL promoted intestinal tumor progression and increased tumor burden." (PMID 33767595, 2021). "Thus, our findings emphasized that loss of MLKL in intestinal tumors exhibited aggressive disease." (PMID 33767595, 2021). "In summary, MLKL exhibits a suppressive effect in the progression of intestinal tumors by regulating the IL-6/JAK2/STAT3 axis." (PMID 33767595, 2021). "The contribution of the cell-specific function of MLKL to the suppression of intestinal tumors needs to be further investigated using MLKL conditional knockout mice in future studies." (PMID 33767595, 2021). "Our results also highlight that interfering with IL-6/STAT3 axis could be a better therapeutic option for intestinal tumor patients with low MLKL expression." (PMID 33767595, 2021). "To further confirm the role of MLKL on STAT3 activation during intestinal tumorigenesis, we examined STAT3 activation in 16-week-old Apcmin/+Mlkl-/- and Apcmin/+ intestinal tumors." (PMID 33767595, 2021).
intracerebral hemorrhage (1 paper, 2024). A cerebrovascular disorder characterized by bleeding into one or both cerebral hemispheres including the basal ganglia and the cerebral cortex. "However, the mechanisms by which MLKL functions in the process of intracerebral hemorrhage (ICH)-induced damage remain unclear." (PMID 39902279, 2024).
kidney injury (1 paper, 2019). Trauma to the kidney. "RIPK3 and MLKL are activated during acute kidney injury, where MLKL is expressed on the apical membrane of proximal tubules." (PMID 31766571, 2019).
lichen planus (1 paper, 2022). A chronic, recurrent, pruritic inflammatory disorder of unknown etiology that affects the skin and mucus membranes. "Mixed supernatant of T cells derived from the lesions of lichen planus and lupus erythematosus induced phosphorylation of RIPK3 and MLKL in keratinocytes, but the inducing effect is dependent on the presence of TNF-α and IFN-γ in supernatant." (PMID 36344541, 2022).
lipid metabolic disorders (1 paper, 2022). "MLKL inhibition had protective effects on lipid metabolic disorder initiated by HFD." (PMID 35083817, 2022).
lymph node metastasis (1 paper, 2018). "The meta-analytic results showed that decreased expression level of MLKL was significantly associated with advanced tumor stage (OR = 1.81, 95% CI: 1.09–3.01, p = 0.021), more lymph node metastasis (OR = 3.83, 95% CI: 2.29–6.40, p < 0.001) and older age (OR = 1.93 95% CI: 1.28–2.93, p = 0.002)." (PMID 30005626, 2018). "Moreover, the expression level of MLKL was associated with clinicopathological features including TNM stage, lymph node metastasis and age." (PMID 30005626, 2018).
lymphopenia (1 paper, 2022). Reduction in the number of lymphocytes. "Collectively, caspase-8 cleavage together with RIPK3 or MLKL suppresses the intrinsic lymphopenia of hematopoietic stem cells." (PMID 35064213, 2022). "We demonstrated an unexpected role of caspase-8 auto-cleavage cooperating with RIPK3 or MLKL and RIPK1 in lymphopenia regulation." (PMID 35064213, 2022).
motor neuron disease (1 paper, 2020). "The role of necroptosis in ALS remains controversial, as motor neuron disease in murine models is independent of necroptosis signaling and MLKL activation." (PMID 32629888, 2020).
myonecrosis (1 paper, 2022). "In polymyositis, few myofibres are immunoreactive to antibodies directed against RIPK3 and MLKL, and myonecrosis is reduced in a mouse model for C protein-induced myositis depleted for MLKL and RIPK3." (PMID 36613804, 2022).
neuropathic pain (1 paper, 2023). Chronic pain caused by damage to nerve fibers. "Analyzing the genetic expression of proteins key to the TNF-α-necroptosis pathway in CCI and SNI neuropathic pain models, we detected the expression and cell localization of necroptosis-related proteins, including RIP1/p-RIP1, RIP3/p-RIP3, and MLKL/p-MLKL, in the ACC of SNI rats." (PMID 37895135, 2023).
ocular infection (1 paper, 2022). "Since RIPK3 or MLKL deficient mice are viable, such mice would provide insights into the contribution of RIPK3-MLKL mediated necroptosis to HSV1 ocular infection." (PMID 35464953, 2022).
osteoporosis (1 paper, 2021). A condition of reduced bone mass, with decreased cortical thickness and a decrease in the number and size of the trabeculae of cancellous bone (but normal chemical composition), resulting in increased fracture incidence. "Studies have found that excessive alcohol consumption leads to activation of RIPK1/RIPK3/MLKL signaling which increases necrotrophic apoptosis of osteoblasts and reduces osteogenic differentiation and bone formation in vivo and in vitro, leading to the development of osteoporosis." (PMID 35118075, 2021).
periapical periodontitis (1 paper, 2022). Inflammation of the periapical tissue. "We found that the phosphorylation levels of RIPK3 and MLKL were elevated in periapical lesion specimens of patients with refractory periapical periodontitis." (PMID 35708336, 2022). "We investigated whether the RIPK3/MLKL signaling pathway was activated in periapical lesion specimens obtained from patients diagnosed with refractory periapical periodontitis." (PMID 35708336, 2022). "Our study revealed that RIPK3/MLKL-mediated macrophage necroptosis contributes to the development of refractory periapical periodontitis and suggests that inhibitors or treatments targeting necroptosis represent a plausible strategy for the management of refractory periapical periodontitis." (PMID 35708336, 2022).
pituitary adenoma (1 paper, 2022). "Based on our data, the expression level of MLKL was significantly decreased in pituitary tumors which was associated with reduced level of pMLKL protein in pituitary adenoma tissues." (PMID 34983494, 2022). "The simultaneous down-regulation of MLKL protein in pituitary adenoma tissues was observed which was in line with its gene expression." (PMID 34983494, 2022). "According to delineate the MLKL expression pattern in pituitary adenoma tissues, a question might be raised that whether the MLKL-reduced mRNA level is accompanied with low MLKL protein level in pituitary adenomas." (PMID 34983494, 2022). "According to our data, the reduced expression of necroptosis mediators (RIP3K, MLKL) in pituitary adenoma reinforces the hypothesis that the necroptosis pathway can be effective in regulating the proliferation and growth of pituitary tumor cells and tumor recurrence." (PMID 34983494, 2022).
pituitary tumor (1 paper, 2022). A benign or malignant neoplasm affecting the pituitary gland. "Also, the MLKL gene expression level in invasive pituitary tumors was correlated significantly with MLKL protein level in NFPA (P = 0.0243) and GHPPA (P = 0.0308) tumors." (PMID 34983494, 2022). "Based on our data, the remarkable reduction in RIP3K and MLKL expression were detected in nonfunctional and GH-secreting pituitary tumors compared to pituitary normal tissues." (PMID 34983494, 2022).
pneumococcal meningitis (1 paper, 2022). An acute purulent infection of the meninges and subarachnoid space caused by Streptococcus pneumoniae, most prevalent in children and adults over the age of 60. "Moreover, although our findings suggest that necroptosis or the necroptosis-like pathway plays an important role in the host defense against pneumococci during pneumococcal meningitis, we could not identify a zebrafish ortholog for MLKL." (PMID 36543127, 2022).